NFIX (nuclear factor I X)
Description:
Recognizes and binds the palindromic sequence 5'-TTGGCNNNNNGCCAA-3' present in viral and cellular promoters and in the origin of replication of adenovirus type 2. These proteins are individually capable of activating transcription and replication.
Synonyms: NF1-X; CTF; NF-I/X; NF1A; MALNS; MRSHSS; SOTOS2
Tractability: PROTAC: UniProt records ubiquitination sites on it; ubiquitination databases record sites on it; its protein half-life has been measured.
Gene: Protein-coding gene on chromosome 19 (12,995,475 to 13,098,796, forward strand). Ensembl gene ENSG00000008441.
Subcellular location: Nucleus
Subcellular location (Human Protein Atlas): Nucleoplasm
Pathways (Reactome):
Gene expression (Transcription): RNA Polymerase III Abortive And Retractive Initiation; RNA Polymerase III Transcription Termination
Gene Ontology:
Molecular function: protein binding; sequence-specific double-stranded DNA binding; DNA-binding transcription factor activity; DNA-binding transcription factor activity, RNA polymerase II-specific; RNA polymerase II cis-regulatory region sequence-specific DNA binding
Biological process: negative regulation of transcription by RNA polymerase II; positive regulation of transcription by RNA polymerase II; regulation of transcription by RNA polymerase II; transcription by RNA polymerase II; positive regulation of DNA-templated transcription; regulation of DNA-templated transcription
Cellular component: nucleoplasm; chromatin; nucleus
Genetic constraint (gnomAD): Loss-of-function variants: 1 observed, 51.81 expected, observed/expected ratio (o/e) 0.0193, 90% interval 0.006 to 0.092. The synonymous counts are far from expectation, so gnomAD's model fits this gene poorly and the ratio says little. Missense variants: 302 observed, 686.56 expected, observed/expected ratio (o/e) 0.44, 90% interval 0.4 to 0.48. Synonymous variants: 240 observed, 297.05 expected, observed/expected ratio (o/e) 0.81, 90% interval 0.73 to 0.9.
Gene-disease validity (ClinGen):
ClinGen rates the evidence that NFIX causes each of these diseases.
Malan overgrowth syndrome (autosomal dominant): Definitive. A rare multisystemic genetic disorder characterized by a characteristic facial features with macrocephaly, overgrowth in infancy, intellectual disability and behavioral problems including anxieties and aggressiveness.
Marshall-Smith syndrome (autosomal dominant): Definitive. Marshall-Smith syndrome is a rare genetic disease characterized by tall stature and advanced bone age at birth.
Homologues: Orthologues: chimpanzee NFIX (98% identical), dog NFIX (98% identical), mouse Nfix (97% identical), guinea pig NFIX (93% identical), macaque NFIX (84% identical), rat Nfix (84% identical), tropical clawed frog nfix (83% identical), pig NFIX (76% identical), zebrafish nfixb (68% identical), zebrafish nfixa (68% identical), Drosophila melanogaster NfI (45% identical), Caenorhabditis elegans nfi-1 (35% identical). Paralogues in human: NFIA (72% identical), NFIC (59% identical), NFIB (58% identical).
Diseases named in the same sentence as NFIX in open-access papers:
NFIX is named in the same sentence as 101 diseases in open-access papers, as found by Europe PMC text mining. Sharing a sentence is not in itself a finding about the gene and the disease. The quoted sentences say what the papers report.
Malan syndrome (28 papers, 2014 to 2026). "Here, we present the case of a Japanese male infant with Malan syndrome, which was caused by a novel frameshift variant resulting from an eight-base insertion in Exon 2 of the NFIX gene." (PMID 42311878, 2026). "Malan syndrome is a rare overgrowth disorder caused by deletions or pathogenic variants in the NFIX gene." (PMID 42311878, 2026). "Reviewed the clinical diagnosis and treatment processes of the Malan syndrome proband, analyzing the relationship between NFIX frameshift mutation genotypes and clinical phenotypes, and the inheritance pattern." (PMID 41282483, 2025). "Cumulative evidence has revealed a spectrum of pathogenic NFIX variants underlying Malan syndrome, encompassing: frameshift, deletion, nonsense, and splice-site mutations." (PMID 41282483, 2025). "NFIX encodes a transcription factor and is associated with AD Marshall-Smith syndrome and Malan syndrome (Sotos syndrome 2), and is highly expressed in the brain cerebellum." (PMID 40593860, 2025). "According to the OMIM database, NFIX gene mutations can cause two clinically overlapping syndromes: Malan syndrome and Marshall-Smith syndrome." (PMID 41282483, 2025). "In summary, this study reported a Malan syndrome pedigree caused by a frameshift mutation in the NFIX gene." (PMID 41282483, 2025). "Background/Objectives: Malan syndrome (MALNS) is an ultra-rare genetic disorder caused by aberrations in the NFIX gene, located at chromosome 19p13.2." (PMID 40003249, 2025). "NFIX mutations are primarily associated with two autosomal dominant disorders: Marshall-Smith syndrome and Malan syndrome." (PMID 41282483, 2025). "Seizures, which reportedly occur in 13% to 63% of individuals with Malan syndrome, are more common in those with NFIX deletions compared to those with NFIX mutations." (PMID 39518712, 2024). "Background and Objectives: Malan syndrome is a rare overgrowth syndrome resulting from NFIX haploinsufficiency due to heterozygous loss-of-function mutations or microdeletions of NFIX on chromosome 19 at p13.2." (PMID 39518712, 2024). "Here, we report a case of Malan syndrome caused by a 75 kb heterozygous microdeletion on the short arm of chromosome 19 at p13.2 involving exons 3 to 11 of NFIX, the smallest microdeletion in this gene reported thus far." (PMID 39518712, 2024). "In humans, point mutations or deletions in the NFIX gene lead to Sotos syndrome, Malan syndrome, or Marshall-Smith syndrome, diseases with neurological and skeletal abnormalities." (PMID 37316562, 2023). "NFIX encodes nuclear factor I/X and was reported as a causative gene for Sotos-like phenotypes (known as Sotos syndrome 2 or Malan syndrome (OMIM #614753)." (PMID 36833222, 2023). "Herein, we report an additional set of sisters with the same novel pathogenic variant in NFIX and clinical features consistent with Malan syndrome providing evidence of germline mosaicism." (PMID 36437934, 2022). "Malan Syndrome (MS) is an ultra-rare overgrowth genetic syndrome due to heterozygous variants or deletions in the Nuclear Factor I X (NFIX) gene." (PMID 35887841, 2022). "Mutation of the NFIX gene in humans is associated with Sotos Syndrome 2; a developmental disorder characterized by excessive growth and advanced bone age, and patients exhibit accelerated epigenetic aging." (PMID 35449380, 2022). "Malan syndrome is an autosomal dominant disorder caused by pathogenic variants in NFIX with less than 100 cases reported thus far." (PMID 36437934, 2022). "Haploinsufficiency of NFIX causes Sotos syndrome 2 (MIM #614753), which is characterized by postnatal overgrowth, macrocephaly, DD, and intellectual impairment." (PMID 34858471, 2021). "NFIX haploinsufficiency or point mutations, clustered mostly in exon 2, are the leading causative mechanism in Malan syndrome." (PMID 31574590, 2019).
Malan syndrome (continued). "Understanding these diverse roles of Nfix will allow insight into human congenital disorders caused by mutations in NFIX, such as Marshall-Smith syndrome and Malan syndrome." (PMID 30081965, 2018). "Together with the patient cohort presented here, a total of 51 different intragenic NFIX variants have been reported in 56 unrelated patients with Malan syndrome." (PMID 29897170, 2018). "NFIX variants that cause Malan syndrome are typically located in exons coding for the DNA binding and dimerization domain, with few exceptions." (PMID 29897170, 2018). "The discovery of NFIX as a causal gene for Malan syndrome also provides a success example for the microarrays-based candidate gene strategy in the identification of Mendelian disease-genes." (PMID 27688808, 2016). "Notably, among the pathogenic variants, the de novo DmisB identified in exon 2 of NFIX prompted us to reassess the phenotype of the proband in Fam81, leading to a clinical diagnosis of Malan syndrome." (PMID 38519481, 2024). "Malan syndrome (MALNS) is an ultra-rare genetic disorder caused by heterozygous chromosomal microdeletions involving the 19p13.2 region or loss-of-function variants in the NFIX gene." (PMID 39816865, 2023). "Alignment of the corresponding mutated NFIX proteins in Malan syndrome and Marshall‐Smith syndrome predicts that despite the overlap in the genomic positions of variants, the position of the translational stop codon strictly separates Marshall‐Smith syndrome—from Malan syndrome‐associated variants." (PMID 29897170, 2018). "Haploinsufficiency of NFIX has been proposed as leading causative mechanism in Malan syndrome." (PMID 29897170, 2018). "Furthermore, through in vitro expression assays and degradation pathway analyses, it was demonstrated that heterozygous NFIX mutations trigger proteasomal degradation, resulting in NFIX haploinsufficiency-ultimately driving the molecular pathogenesis of Malan syndrome." (PMID 41282483, 2025). "It has been established that mutation of NFIX (Nuclear Factor I X; OMIM 164005) at chromosomal locus 19p13 underlies the pathogenesis of Malan syndrome (OMIM 614753)." (PMID 41282483, 2025). "The other two frameshift GZF1 p.[His407Profs*61] and NFIX p.[Pro249Metfs36] pathogenic variants causing JLSM (Patient 1) and Malan syndrome (Patient 2) are novel genotypes." (PMID 38909058, 2024). "(2013) reported two sisters with Malan syndrome and a partial NFIX deletion, suggesting germline mosaicism in one of the parents." (PMID 29897170, 2018). "To date, two Sotos-like overgrowth syndromes called as Sotos syndrome 2 (SOTOS2; OMIM 614753) and 3 (SOTOS3; OMIM 617169) have been reported, which are caused by mutations in the NFIX and APC2 genes, respectively." (PMID 28665350, 2017). "In this study, we report two patients with distinct overgrowth syndromes, Malan syndrome (19p13.2 deletion of NFIX) and Sotos Syndrome (5q35.2 deletion of NSD1)." (PMID 27688808, 2016). "The current study suggests that NFIX mutations triggering or evading NMD can lead to two different clinical phenotypes, Malan syndrome or Ma Shi syndrome, with Malan syndrome having overgrowth as the main phenotype caused by a major NFIX single-dose insufficiency." (PMID 41282483, 2025). "Malan syndrome (MALNS) (MIM 614753) is an ultra-rare genetic disorder (1/1,000,000) caused by heterozygous chromosomal microdeletions involving the 19p13.2 region or loss-of-function (LoF) variants in the NFIX gene (nuclear factor I X) (OMIM 164005)." (PMID 39816865, 2023). "Malan syndrome is characterised as an overgrowth disorder presenting unusual facial phenotypes, intellectual disability and behavioural abnormalities, and is a result of NFIX haploinsufficiency." (PMID 35954220, 2022). "We identified a 990 kb deletion including the NFIX gene in a patient with Malan syndrome." (PMID 31574590, 2019).
Malan syndrome (continued). "We compared the findings in Malan syndrome to those reported in Marshall‐Smith syndrome, an allelic disorder caused by variants in NFIX that is postulated to result from a dominant‐negative action." (PMID 29897170, 2018). "Although the pathogenic mechanisms of Malan syndrome have not been fully elucidated, most researchers contend that haploinsufficiency and point mutations in the NFIX gene constitute the major cause of this disorder; however, specific mechanisms require further investigation." (PMID 41282483, 2025). "The NFIX c.164delC p.Ala55Glyfs*2 frameshift mutation did not significantly affect mRNA expression levels, but induced protein degradation via the ubiquitin-proteasome pathway, resulting in haploinsufficiency and ultimately causing Malan syndrome." (PMID 41282483, 2025). "The nuclear factor I/X (NFIX) gene encodes a ubiquitously expressed transcription factor whose mutations lead to two allelic disorders characterized by developmental, skeletal, and neural abnormalities, namely, Malan syndrome (MAL) and Marshall–Smith syndrome (MSS)." (PMID 37283649, 2023). "Therefore, it is plausible that Malan syndrome patients may have abnormal ependymal cell junctions and cilia, which may contribute to the expansion of the ventricles, even with heterozygous NFIX expression." (PMID 35954220, 2022).
breast carcinoma (15 papers, 2014 to 2025). "In this study, we examined the role of NFIX in breast cancer progression and the underlying molecular mechanisms." (PMID 40000619, 2025). "In the present study, high expression of NFIA, NFIB and NFIX was significantly associated with improved prognosis in breast cancer." (PMID 32219034, 2020). "Similarly, another study found that NFIX upregulation is associated with poor prognosis in breast cancer because of its role in ROS status." (PMID 36901722, 2023). "Furthermore, patients with high NFIX expression have a better prognosis, suggesting that NFIX may be associated with breast cancer progression." (PMID 40000619, 2025). "Moreover, NFIX expression in breast cancer is associated with methylation of its promoter region." (PMID 40000619, 2025). "We intervened in the expression of NFIX by transfecting stable overexpression plasmids or downregulation plasmids into breast cancer cell lines." (PMID 40000619, 2025). "In summary, these results indicate that overexpression of NFIX inhibited breast cancer cell proliferation in vitro and in vivo." (PMID 40000619, 2025). "NFIX exhibits decreased expression in breast cancer cells, and it impedes breast cancer progression by targeting CDK1 and triggering a G2/M cell cycle arrest." (PMID 40000619, 2025). "To summarize, the methylation level of NFIX in breast cancer increases, leading to its downregulation." (PMID 40000619, 2025). "To investigate the role of NFIX in breast cancer proliferation, we examined its expression of NFIX in normal breast cell lines and breast cancer cell lines." (PMID 40000619, 2025). "Our study demonstrated that NFIX plays a critical role in CDK1-regulated cell cycle transitions and determined that NFIX inhibits cell proliferation in breast cancer." (PMID 40000619, 2025). "BSP sequencing was employed to determine the methylation status of the NFIX promoter in two paired cases of breast cancer tissues and breast cancer cell lines." (PMID 40000619, 2025). "In summary, these results suggest that overexpression of NFIX leads to G2/M phase arrest in breast cancer cells." (PMID 40000619, 2025). "To understand the role of NFIX in breast cancer and its potential as a therapeutic target, we first examined the RNA sequencing data of breast cancer (BC) from The Cancer Genome Atlas (TCGA)." (PMID 40000619, 2025). "Our study reveals for the first time that NFIX expression is downregulated in breast cancer tissues and cell lines." (PMID 40000619, 2025). "We predicted the CpG islands in the promoter region using the Methprimer website and found that NFIX was hypermethylated in breast cancer tissues as well as in breast cancer cell lines, as determined by BSP sequencing." (PMID 40000619, 2025). "The RT-qPCR results indicated that NFIX was expressed at low levels in breast cancer, with the lowest expression observed in the MCF7 cell line compared to the other cell lines." (PMID 40000619, 2025). "Conversely, NFIX inhibits breast cancer cell proliferation by delaying mitotic entry via CDK1 suppression." (PMID 40746552, 2025). "We found that NFIX was significantly downregulated in breast cancer samples compared with adjacent normal samples." (PMID 40000619, 2025). "Our results indicate that NFIX expression is downregulated in breast cancer tissues, and overexpression suppresses cancer cell proliferation by inhibiting the G2/M phase transition of the cell cycle." (PMID 40000619, 2025). "We then analyzed NFIX expression in 20 paired breast cancer tissues using RT-qPCR and immunohistochemistry experiments and found lower levels of NFIX expression in BC tissues compared with normal tissues, confirming the results in the database." (PMID 40000619, 2025). "Next, we further validated the role of NFIX in breast cancer proliferation through in vivo animal experiments." (PMID 40000619, 2025).
breast carcinoma (continued). "NFIX acts as a transcription factor to regulate the expression of downstream genes and can also interact with target proteins to promote their ubiquitination and degradation, providing clues about the roles of NFIX in breast cancer biology." (PMID 40000619, 2025). "Therefore, cellular functional experiments are needed next to verify the role of NFIX in breast cancer development, and further studies are required to determine the mechanisms by which NFIX acts." (PMID 40000619, 2025). "Furthermore, proliferation assays and in vivo experiments similarly demonstrated that YBX1 attenuated the influence of NFIX on breast cancer cells." (PMID 40000619, 2025). "Additionally, we found that the expression of NFIX in breast cancer was significantly negatively correlated with its methylation status." (PMID 40000619, 2025). "NFIX is downregulated in breast cancer compared to normal breast tissue, which impacts prognosis." (PMID 40000619, 2025). "The results showed that the downregulation of NFIX promoted the growth of breast cancer cells." (PMID 40000619, 2025). "The results suggest that the expression of NFIX in breast cancer may correlate with the degree of methylation of the NFIX promoter." (PMID 40000619, 2025). "To confirm that NFIX expression in breast cancer is regulated by methylation, we treated normal breast epithelial cell lines and wild-type breast cancer cell lines with the DNA methyltransferase inhibitor AZA at concentrations of 0, 0.5, 1.0, 1.5, 2.0, and 2.5 μM." (PMID 40000619, 2025). "Among all NFI members, the expression of NFIX was noticeably lower in breast cancer." (PMID 40000619, 2025). "Moreover, the overexpression of acyl-CoA synthetase 4 in the MCF-7 breast cancer cell line leads to changes in various developmental pathways, including the overactivation of NFIX and its target gene ENO3." (PMID 36901722, 2023). "However, the role of NFIX in breast cancer has received less attention." (PMID 40000619, 2025). "Thus, NFIX is a potential biomarker and molecular target for the treatment of breast cancer." (PMID 40000619, 2025). "With regard to lnc-MAFG-AS1, it exhibits tumorigenesis by regulating the miR-574/SOD2 axis in breast cancer; it also reverses miR-34a maturation to induce glioblastoma growth; besides, it accelerates pancreatic cancer progression by binding miR-3196 to outburst NFIX." (PMID 36034393, 2022). "To further investigate the functions of NFIX in the breast cancer cell cycle, we performed a cell synchronization experiment using MCF7-NFIX and MCF7-Vector cells to analyze the cell cycle transitions." (PMID 40000619, 2025). "These genes included BPTF, PHF5A, and SPG7 in cancer of female genital organs, as well as FGF10, NFIX, and SCAP in breast cancer." (PMID 38409266, 2024). "Above all, NFIX is closely related to biogenesis, development, and cancer growth but has not been studied in breast cancer." (PMID 40000619, 2025). "Currently, research on the role of NFIX in breast cancer remains limited, and its molecular mechanisms are not yet fully elucidated." (PMID 40000619, 2025). "Typically, cancer driver genes NFIX and CDH4 may act as methylation biomarkers for early detection for breast cancer and gastrointestinal tumorigenesis." (PMID 34323415, 2021). "Of these genes, NFIX and PITX2 might be used as early detection and prognostic markers for breast cancer." (PMID 34323415, 2021). "Finally, only 1 (BCAS4/BCAS3), 1 (BSG/NFIX), 2 (STX16/RAE1, RAB22A/MYO9B) and 0 fusions have been reported by all the tools within the considered breast cancer cell lines." (PMID 28114882, 2017).